IL1A (interleukin 1 alpha)
Diseases named in the same sentence as IL1A in open-access papers (continued):
Sharing a sentence is not in itself a finding about the gene and the disease.
colitis (continued). "In colonic tumorigenesis, the inflammatory cells contributed to the colitis by generating proinflammatory cytokines, such as IL-1α, IL-2, IL-6, TNF-α, INF-γ." (PMID 29162930, 2017). "Anakinra blocks both IL-1α and IL-1β, but in the mouse model described, experimental specific IL-1α antibodies were significantly more efficacious in reducing severity of colitis compared to external IL-1 receptor antagonist (IL-1RA)." (PMID 28288653, 2017). "The plasma levels of IL-17, KC, IL-1a and IL-4 tended to decrease in the colitis mice fed a SD and subjected to voluntary exercise as compared to the non-exercising mice (p < 0.05) but that change was insignificant." (PMID 28425943, 2017). "Many of the inflammatory cytokines attenuated by FFAR2 and FFAR3, including C5, CCL1, CCL2, GM-CSF, IL-1α, IL-1β, ICAM-1 and TNF, are associated with colitis." (PMID 27667443, 2016). "MOS administration attenuated colitis-related increase of Coliforms, normalized colonic muc2 expression and attenuated local expression of proinflammatory cytokines IL-1a, IL1b, IL6, KC, G-CSF and MCP1 as well as toll-like receptor TLR4 and NLRP3 inflammasome." (PMID 27658624, 2016). "Compared to untreated colitis, both oral fucoidan extracts significantly lowered the levels of IL-1α, IL-1β, IL-10, MIP-1α, MIP-1β, G-CSF and GM-CSF." (PMID 26083103, 2015). "In this innate immune model of colitis, Tpl2−/− mice experienced milder colitis compared to wild type mice with reduced production of inflammatory cytokines IL-1α, IL-1β, IL-6, and IL-17, as well as reduced production of the anti-inflammatory cytokine IL-10." (PMID 25781948, 2015). "A recent study, however, also provides evidence that during acute experimental colitis, IL-1α is potently produced by the intestinal epithelium." (PMID 23847622, 2013). "Neutralizing antibodies (e.g., FLO1 mAb) could disrupt IL-1α-driven barrier dysfunction while promoting probiotic enrichment, as evidenced by reduced ileitis/colitis severity upon blockade." (PMID 40661957, 2025). "In addition, MCC950, a chemical NLRP3 inhibitor, can significantly suppress the release of the pro-inflammatory cytokines IL-1β, IL-18, and IL-1α in colitis." (PMID 37240022, 2023). "Furthermore, the therapeutic efficacy of Eat2 was associated with decreases in IL-1α and IL-6 levels detected in colonic homogenates from mice with TNBS colitis." (PMID 32332834, 2020). "Cohousing of IL-1α KO with WT mice diminishes their resistance to DSS-induced colitis." (PMID 29766049, 2018). "As we have previously shown, IL-1α KO mice are resistant to DSS-induced colitis." (PMID 29766049, 2018). "In contrast, goblet cells were not significantly affected after recovery from colitis in IL-1α-deficient mice." (PMID 29766049, 2018). "We previously demonstrated that IL-1α acts as a proinflammatory modulator of DSS-induced colitis." (PMID 29766049, 2018). "Furthermore, IL-33 signaling protects from murine oxazolone colitis by supporting intestinal epithelial function, and IL-33 promotes IgA production to maintain gut microbial homoeostasis and restrain IL-1α-dependent colitis." (PMID 28423665, 2017). "In concordance with the TNBS-colitis model, both IL-1α and IL-1β are elevated in IBD." (PMID 23382912, 2013). "In this model, both IL-1α and IL-1β are increased in the inflamed intestinal tissues and display pro-inflammatory properties, as neutralization by either endogenous or exogenous IL-1Ra administration resulted in significant amelioration of colitis." (PMID 23847622, 2013). "Our findings that L-Arg also effectively reduced other proinflammatory mediators, such as the innate immune cell products IL-1α, IL-1β, and IL-6, as well as the prototype Th17 cytokine, IL-17, suggest that it may be broadly beneficial in colitis." (PMID 22428068, 2012).
colitis (continued). "B. vulgatus mpk mono-colonized mice only showed expression of IL-6 mRNA, whereas E. coli mpk mono-colonized mice, prone to develop colitis and SPF IL-2−/−-mice already suffering from colitis, revealed high levels of IL-1α, IL-1β, TNF-α, IFN-γ, IL-10 and IL-6 mRNA in the intestine." (PMID 18545662, 2008). "Compared with the CT group, a colitis model was successfully constructed in the DSS group, as evidenced by higher weight loss, an increased DAI, shorter colon length, more serious colonic tissue damage, and higher levels of pro-inflammatory cytokines (IL-6, IL-1β, TNF-α, and IL-1α)." (PMID 37505716, 2023). "EVs decreased NF-κB levels and mRNA levels of TNFα, IL-1α, IL-1β and IL-2, and increased mRNA levels of TGFβ and IL-10 in LPS-induced inflammation in human intestinal epithelial cells (HT-29) and reduce inflammation symptoms of dextran sulfate sodium-induced colitis in mice." (PMID 35432276, 2022). "Moreover, chemical-induced colitis in the VDR knockout mice was accompanied by high colonic expression of inflammation, including TNF-α, IL-1α, IL-1β and IL-8, leading to weight loss, ulceration and perforation of the bowel, endotoxemia and increased mortality." (PMID 34576700, 2021). "However, serum levels of IFN-γ, IL-1α, IL-6, and IL-17 were elevated at baseline in the serum of T/I mice (these mice had colitis at the time of assessment) compared with WT mice and IFN-γ and IL-17 did not significantly increase in the serum of T/I mice following challenge with LPS." (PMID 22848611, 2012). "Its underrecognized role in CD pathogenesis has been highlighted by studies demonstrating that damaged intestinal epithelial cells (IECs) release substantial IL-1α during spontaneous ileitis and DSS-induced colitis." (PMID 40661957, 2025). "In our experimental conditions, GILZp, by dampening IL-1α and TNFβ levels and increasing MUC2 transcription, improved the symptoms of colitis, thus helping resolve inflammation and probably stimulating mucus production." (PMID 39456254, 2024). "Similar to the reported effects of MSCs in chemically-induced colitis, BM-MSC treatments in Winnie mice downregulated the expression of Il6, Ifng, Il1b, Il1a, Tnf, Cxcl2, Tbx21 and Itgam, which were upregulated in Winnie mice and IBD patients." (PMID 38503815, 2024). "The expression of Il1a, Ccl5, Il1b, Ccl3, and Cxcl1 were significantly elevated in CD45+ cells from Il17b-/- colitis mice (P < 0.05)." (PMID 36814913, 2023). "The deficiency of CXCL13 resulted in significantly decreased expression of inflammatory cytokines IL-21, IL-1β, IL-1α, IL-17, IL-6 and TNF-α in colon sites of mice with colitis." (PMID 36172372, 2022). "The present study confirmed and extended this effect by detecting a substantial reduction of IL-1α, IL-1β, IL-6, TNF-α, INF-γ, G-CSF, IL-13, GM-CSF, IL-3, MIP-1α, RANTES, and eotaxin cytokines in response to UTA77 treatment in both colitis models." (PMID 34497514, 2021). "Some reports found that IL-1β enhanced colitis severity in animal models, while others reported that Il1β-/- and Il1r1-/-, the IL-1α and IL-1β receptor, mice displayed exacerbated severity in DSS-induced colitis." (PMID 34721422, 2021). "In one TNBS-colitis model, n-3-PUFA was found to increase TLR-2 and IL-1A gene expression in rat colon tissue, whereas n-9 increased TLR-4 expression." (PMID 33603741, 2020). "Consistent with the results of a previous experiment, increased levels of the cytokines IL1α, TNF‐α, IL6, IL12P40 and MIP‐1A were observed in mice with DSS‐induced colitis." (PMID 32363766, 2020). "The pro‐inflammatory cytokines (IL1A, IL1B and IL‐6), neutrophils and bacterial infiltration were significantly increased in CD11c‐Cre+Rab32f/f mice with colitis induced by DSS." (PMID 30338217, 2018). "This study shows a strong and novel correlation between IL-1α expression, microbiota composition, and clinical outcomes of DSS-induced colitis." (PMID 29766049, 2018).
colitis (continued). "IMPORTANCE Here, we show a connection between IL-1α expression, microbiota composition, and clinical outcomes of DSS-induced colitis." (PMID 29766049, 2018). "Overall, we show in this study a strong and novel correlation between IL-1α function, microbial composition, and clinical outcomes of DSS-induced colitis." (PMID 29766049, 2018). "We demonstrate that host-derived IL-1α has a clear influence on gut microbiota composition, as well as on severity of DSS-induced acute colon inflammation." (PMID 29766049, 2018). "We analyzed the gut microbiota composition in both control (WT) and IL-1α KO mice under steady-state homeostasis, during acute DSS-induced colitis, and after recovery using 16S rRNA next-generation sequencing." (PMID 29766049, 2018). "Here, we show a connection between IL-1α expression, microbiota composition, and clinical outcomes of DSS-induced colitis." (PMID 29766049, 2018). "Up-regulated genes in both TNBS-colitis and human IBD included ADA, PrPc, and IL-1α, while down-regulated genes consisted of aldehyde dehydrogenase 1 family, member A1 (ALDH1A1), and PPARγ." (PMID 23382912, 2013). "F. nucleatum infection facilitates inflammation in acute colitis with IL-1α from colon tissue by activating noncanonical inflammasome through gasdermin D cleavage." (PMID 40260115, 2025). "Additionally, anti-IL-1α treatment ameliorated chronic ileitis and protected mice from developing acute DSS-induced colitis." (PMID 39935485, 2025). "The key cytokines involved in colitis, such as TNF-α, IL-17A, and IL-1α, were used to test whether DSS-induced downstream cytokines restricted NEDD4L expression." (PMID 39688910, 2024). "The elevated levels of IL-1α, IL-1β, IL-3, IL-6, IL-9, IL-12 (P40), IL-12 (P70), IL-17, GM-CSF, and G-CSF in response to DSS treatment in the current study, supports the strong involvement of macrophage activation in the DSS induced colitis model." (PMID 36365201, 2022). "The aggravated colitis in mice lacking IL-38 was accompanied by a greater increase in the pro-inflammatory cytokines IL-1α and IL-1β in the colon compared to WT mice." (PMID 35693797, 2022). "Additionally, activation of PXR suppresses the expression of NF-κB target genes including iNOS, IL-1α, IL-1β, IL-6 and TNF-α in the colon of DSS colitis mice." (PMID 31719637, 2019). "Importantly our results demonstrated that MCC950 treatment significantly reduced IL-1β, IL-1α, IL17, IL6, IFN-γ, TNF-α and MIP1a in the colitis colon)." (PMID 29872077, 2018). "The pro‐inflammatory cytokines IL1A, IL1B, IL6, and CSF3 and chemokines CXCL1 and CXCL2 were significantly increased, and the frequency of CD11b+Ly6G+ neutrophils was higher in CD11c‐Cre+Rab32f/f colitis mice." (PMID 30338217, 2018). "Also, in our study, oral enoxaparin reduced the levels of a number of mucosal cytokines including IL-1α, IL-1β, IL-10, MIP-1α, MIP-1β, G-CSF, GM-CSF during colitis." (PMID 26218284, 2015). "In the amygdala, the mutant A allele led to lower levels of IL-1α, IL-9, macrophage inflammatory protein (MIP)-1β, and MIP-2 independent of colitis—providing additional understanding of how FAAH may serve as a regulator of inflammatory responses in the brain." (PMID 34916909, 2021). "In contrast, IL-1β, but not IL-1α, activates IL-6 expression in neurons, selectively mediates the response to vascular injury, while IL-1α- and IL-1β-specific actions have also been identified in acute colon inflammation in mice." (PMID 32468079, 2020). "Cohousing did not cause IL-1α KO mice to respond to DSS in a manner similar to that of WT mice, indicating that additional pathways, besides the microbiota, are involved in the pathogenesis of colitis." (PMID 29766049, 2018). "More important, after mice had recovered from this mild intestinal injury, a subsequent intrarectal administration of IL-1α induced severe colitis, whereas mice that had not undergone prior dextran sulfate sodium–induced tissue remodeling failed to mount an inflammatory response to IL-1α." (PMID 29248462, 2018).
colitis (continued). "The plasma concentrations of IL-17, KC, IL-1a and IL-4 were significantly increased in the sedentary mice with colitis fed a SD as compared to the respective values obtained in the sedentary mice without colitis fed a SD (p < 0.05)." (PMID 28425943, 2017). "Furthermore, while specific blockade of IL-1α leads to amelioration of colitis, administration of IL-1Ra or anti-IL-1β antibodies do not effectively treat DSS colitis." (PMID 23847622, 2013). "The increased IFN-γ and IL-1α that was also observed in the serum of unmanipulated T/I mice may reflect that these mice have (spontaneous) colitis while the other genotypes of mice studied do not, but additional studies will be required to determine the cellular source(s) of these cytokines." (PMID 22848611, 2012). "Similar disease patterns were observed in conditional KO mice lacking IL-1α only in colon epithelial cells, indicating that intestinal epithelial cell-derived IL-1α is the driver of induction of DSS-induced colitis." (PMID 29766049, 2018). "Interestingly, exogenous administration of anti-IL-1α antibodies, but not IL-1Ra, has been shown to ameliorate intestinal inflammation and increase repair and recovery of the epithelial barrier following DSS-induced colitis." (PMID 31231388, 2019).
melanoma (77 papers, 2005 to 2026). A malignant, usually aggressive tumor composed of atypical, neoplastic melanocytes. "The expression of BRAF mutated in melanoma cells induced the up-regulation of IL-1α/β, which promoted the expression of PD-L1 in tumor-associated fibroblasts." (PMID 36016960, 2022). "BRAFV600E mutation induces IL-1α/β secretion by melanoma cells, which triggers increased expression of PD-L1/L2 at the cell surface of CAFs." (PMID 33261061, 2020). "Furthermore, it has been shown that mutation in BRAF induces the production of IL-1α and –β in melanoma cells, which in turn enhances MAF’s capability to suppress the proliferation and function of cytotoxic T cells." (PMID 34067929, 2021). "Furthermore, elevated levels of the proinflammatory proteins present in the “cytokine storm” linked to COVID‐19, such as TNF‐α, IL‐1α, IL‐1β, IL‐6, and ferritin, may have also caused skin depigmentation or hypopigmentation, ultimately resulting in melanoma." (PMID 40270775, 2025). "Specifically, plasma levels of IL-1α, IL-6, IL-17, and TNFα, proinflammatory cytokines, were significantly higher in the Melanoma + Combi-ICI group compared to controls." (PMID 40313772, 2025). "On the other hand, different authors have consistently maintained that EDPs induce the production and/or secretion of IL-1α, IL-1β, and IL-6 in ligamentum flavum cells, synovial cells, and melanoma cell lines." (PMID 38967692, 2024). "Melanoma cells secrete a complex set of proteins controlled by IL1α-NF-κB, and this in turn triggers a positive feedback loop with ROCK-Myosin II that enables recruitment of monocytes and their differentiation into tumor-promoting macrophages." (PMID 38533720, 2024). "Considering the constitutive and high levels of NLRP3 and of IL-1α in melanoma, we investigated the effects of NLRP3 inhibition on STAT3 activity and its phosphorylation." (PMID 36672229, 2023). "In vitro, the human melanoma cell line 1205Lu, stimulated with IL-1α, exhibited significantly lower levels of STAT3 Y705 phosphorylation by the combination treatment, thus affecting the nuclear functions of STAT3." (PMID 36672229, 2023). "OLT1177 also reduces tumor levels of active IL-1α and is highly expressed human melanoma as well as in mouse B16F10 melanoma." (PMID 36672229, 2023). "Further, conditioned medium from the BRAF(V600E) melanoma cells promoted the activation of stromal fibroblasts, an event partially attributable to IL1α/β-mediated modulation of PD-1 ligands in melanoma CAFs." (PMID 37762344, 2023). "In human melanoma cells, blocking the IL-1 pathway by IL-1α or IL-1β treatment increases autophagy-related components such as LC3-I and LC3-II, indicating an increase of autophagy." (PMID 36245983, 2022). "In melanoma, a pro-inflammatory phenotype is induced in astrocytes exposed to melanoma exosomes that included the upregulation of IL-1α, IL-1β, CXCL1 and CCL2 among others." (PMID 36704194, 2022). "In this study, the immune-regulatory ability of melanoma CAFs was demonstrated by the ample production of several cytokines and chemokines, including IL-1α, IL-1β, IL-6, IL-8, and CXCL10." (PMID 34298873, 2021). "The levels of IL-6, IL-8, IL-10, IL-17A, IL-27, IL-31, GM-CSF, IFN-α, IL-9, VEGF-D, TNF-β, NGFβ, IL-23, IL-22, and IL-1α were below the threshold of detection in both melanoma patients and healthy controls." (PMID 33574842, 2021). "Findings that are in line with ours have been reported for cisplatin-treated melanoma models, and with a therapeutic perspective IL1α and CXCL8 were identified as crucial and pharmacologically targetable drivers." (PMID 34911941, 2021).